MYOC (myocilin)
Diseases named in the same sentence as MYOC in open-access papers (continued):
Sharing a sentence is not in itself a finding about the gene and the disease.
myopia (5 papers, 2007 to 2024). "Subject DNA was genotyped with a panel of MYOC single nucleotide polymorphisms (SNPs) including those found previously associated with high myopia." (PMID 19180258, 2009). "In contrast to previously published significant association between MYOC and high myopia in subjects of Chinese ethnicity, this study suggests that there is no such relationship in subjects of Caucasian ethnicity." (PMID 19180258, 2009). "We sought to investigate the association between high myopia and polymorphisms in MYOC in subjects of European ethnicity." (PMID 19180258, 2009). "Herein, association between myocilin polymorphisms and high myopia was examined in two independent Caucasian subject groups." (PMID 19180258, 2009). "Our results suggest that MYOC polymorphisms have a very low, or possibly negligible, influence on high myopia susceptibility in subjects of European ethnicity." (PMID 19180258, 2009). "Association between MYOC polymorphisms and high myopia was first reported in a case-control study of Chinese subjects from Singapore." (PMID 19180258, 2009). "Linkage and association was shown between the MYOC polymorphisms and high myopia in our family-based association study." (PMID 17438518, 2007). "This makes it unlikely that any causative MYOC SNP associated with high myopia would fall outside of this 60 kb region." (PMID 17438518, 2007). "The present study is the largest of these four to test the association between MYOC markers and high myopia in that it involved a total of 162 families with 233 severely myopic offspring." (PMID 17438518, 2007). "Tests of association between MYOC polymorphisms and high myopia." (PMID 19180258, 2009). "Test of association between MYOC and myopia: family data only." (PMID 19180258, 2009). "Association between high myopia and MYOC polymorphisms was assessed using the Unphased program." (PMID 19180258, 2009). "Three small studies tested the association between MYOC and myopia but results conflicted." (PMID 17438518, 2007). "Thus, we hypothesize that polymorphisms in and around the MYOC gene may play a role in myopia susceptibility." (PMID 17438518, 2007). "Research supports the idea that this genetic pathway contributes to the connection between POAG and myopia, as polymorphisms in the TIGR/myocilin gene have been associated with high myopia in population studies." (PMID 39337937, 2024). "It is also noteworthy that some factors that stimulate myocilin expression in TMC have also been implicated in the regulation of postnatal eye growth and myopia, e.g., bFGF, TGF β, and oxidative mitochondrial pathways." (PMID 19180258, 2009). "A final potential reason for our failure to detect an association between MYOC polymorphisms and high myopia is that MYOC may not in fact be a high myopia susceptibility gene (i.e., the significant associations reported previously could have been false positive findings)." (PMID 19180258, 2009). "Thus, the role of MYOC in high myopia in Chinese subjects may be dissimilar to that in Caucasians." (PMID 19180258, 2009).
primary congenital glaucoma (5 papers, 2010 to 2023). "Primary congenital glaucoma is not related to juvenile or adult onset open angle glaucoma linked to the MYOC (TIGR) gene on chromosome 1q25 at locus GLCIA, but in some cases a mutation in the CYP1B1 has been found." (PMID 26451378, 2015). "MYOC and FOXC1 mutations are not involved in pathogenesis of primary congenital glaucoma in our patients." (PMID 21031026, 2010). "This is the first study from north India showing non-involvement of MYOC and FOXC1 in the pathogenesis of primary congenital glaucoma." (PMID 21031026, 2010).
breast carcinoma (3 papers, 2022 to 2025). "Inhibition of Grp94 with small molecules has been shown to reduce cell migration of breast cancer cells and promote degradation of mutant myocilin aggregates." (PMID 41351922, 2025). "The result showed that the protein expression of TUBB3, MCM2, FN1, S100A7, and TFF1 was increased, and the protein expression of MYOC was downregulated in luminal A breast cancer, which was consistent with the result of RNA expression." (PMID 35692369, 2022). "MYOC has been previously reported as a topranked downregulated gene in breast cancer." (PMID 37287543, 2023). "The protein expression results of TUBB3, MCM2, MYOC, FN1, S100A7, and TFF1 were consistent with the mRNA expression result COL10A1, LEP, PLIN1, PGM5-AS1, and TRHDE-AD1 were capable of discriminating luminal A breast cancer and normal controls." (PMID 35692369, 2022).
AIDS (2 papers, 2022). A syndrome resulting from the acquired deficiency of cellular immunity caused by the human immunodeficiency virus (HIV). "In addition, expression of MYOC was elevated in patients with HIV/AIDS." (PMID 35621025, 2022).
Alzheimer disease (2 papers, 2021 to 2025). A progressive, neurodegenerative disease characterized by loss of function and death of nerve cells in several areas of the brain leading to loss of cognitive function such as memory and language. "In contrast to antibodies targeting amyloid-β or tau for the treatment of Alzheimer disease or α-synuclein for the treatment of Parkinson's disease, targeting a specific misfolded myocilin species may not be required to promote mutant myocilin degradation." (PMID 39726989, 2025).
Hepatic fibrosis (2 papers, 2014 to 2022). The presence of excessive fibrous connective tissue in the liver. "We also identified several new genes, such as perilipin-3, legumain, and myocilin, which were associated with liver fibrosis." (PMID 25380136, 2014). "IPA of MYOC/CCL19 fibroblast gene expression correlating with the mRSS revealed several prominent pathways: senescence, hepatic fibrosis signaling, IL-6 signaling, STAT3 signaling, TGF-β signaling, protein ubiquitination, JAK/Stat signaling, and role of JAK1, JAK2 and TYK2 in interferon signaling." (PMID 35943798, 2022).
Hypertension (2 papers, 2019 to 2021). The presence of chronic increased pressure in the systemic arterial system. "However, hypertension was treated in five of the 11 patients with candidate causal MYOC variants." (PMID 30816137, 2019). "Therefore, we compared pERG data obtained from a third cohort of mice (including naïve controls) three weeks after Ad5.MYOC-induced hypertension and eyes injected with Ad5.empty vector." (PMID 34299211, 2021).
lung carcinoma (2 papers, 2022 to 2023). "Some miRNAs found in our analysis that regulate MYOC, KCNQ5, MUC1, and F3 mRNAs has been also described in other cancers, such as colorectal cancer cells and identified as biomarkers in lung cancer, osteosarcoma, ovarian cancer and penile cancer." (PMID 36012492, 2022).
Obesity (2 papers, 2021 to 2023). Accumulation of substantial excess body fat. "In summary, the expression of COBL, MKX and MYOC in AT is related to obesity, AT dysfunction, and the early signs of metabolic disease in children." (PMID 36834493, 2023). "Furthermore, COBL, MKX and MYOC expression in the subcutaneous AT of children is related to obesity and parameters of AT dysfunction and metabolic disease, such as adipocyte size, leptin levels and HOMA-IR." (PMID 36834493, 2023). "Finally, we provide evidence that the expression of COBL, MKX and MYOC in subcutaneous AT is related to obesity, parameters of AT dysfunction, and the early signs of metabolic disease in children." (PMID 36834493, 2023). "When we analyzed a potential association of MYOC expression in SAT of children with obesity and related parameters in general, we did not observe an association with BMI SDS." (PMID 36834493, 2023). "We detected significantly decreased expressions of COBL and MKX in subcutaneous AT samples of children with overweight and obesity compared to lean children, while the expression of MYOC was not altered with obesity." (PMID 36834493, 2023).
achromatopsia (1 paper, 2025). Achromatopsia (ACHM) is a rare autosomal recessive retinal disorder characterized by color blindness, nystagmus, photophobia, and severely reduced visual acuity due to the absence or impairment of cone function. "Recent clinical trials exploring gene therapy use in other ocular regions have emerged, such as achromatopsia and Myocilin-associated Glaucoma (MYOC)." (PMID 41440982, 2025).
acute myeloid leukemia (1 paper, 2022). Acute myeloid leukemia (AML) is a group of neoplasms arising from precursor cells committed to the myeloid cell-line differentiation. "Recent studies have also shown that MEF2C plays an important role in myocilin mediating cancer-induced muscle wasting and cachexia in cancer patients and regulates chemotherapeutic resistance and the disease progression of acute myeloid leukemia." (PMID 36661663, 2022).
albinism (1 paper, 2020). A congenital disorder characterized by partial or complete absence of melanin pigment in the eyes, hair, or skin. "The genes identified for MAC were KMT2D, MAB2IL2, ALDH1A3; ASDA were KERA, PAX6, MYOC, TGFBI, and SLC4A11; congenital cataract were CRYBB2, EPHA2, HSF4 and BCOR; infantile nystagmus were CACNA1A and FRMD7; and albinism were OCA2, GPR143, HPS6 and SLC38A8." (PMID 32830442, 2020).
amyloidosis (1 paper, 2020). A disorder characterized by the localized or diffuse accumulation of amyloid protein in various anatomic sites. "The mutation of myocilin induced a toxic gain in cellular function in the endoplasmic reticulum stress of TM cells through misfolding and abnormal amyloidosis of myocilin protein." (PMID 32714192, 2020).
brain ischemia (1 paper, 2020). Diminished or absent blood supply to the brain caused by obstruction (thrombosis or embolism) of an artery resulting in neurologic damage. "High LPHN3 expression has been previously reported in a transgenic mice model that over-expressed myocilin and in mice after brain ischemia." (PMID 33247693, 2020).
Coats disease (1 paper, 2016). Coats disease (CD) is an idiopathic disorder characterized by retinal telangiectasia with deposition of intraretinal or subretinal exudates, potentially leading to retinal detachment and unilateral blindness. "The down-regulation of MYOC promotes AH outflow, which elevates intraocular pressure and may induce the occurrence of Coat's disease." (PMID 27416065, 2016).
diabetes (1 paper, 2022). "Additionally, other four genes (FCGR1A, NCF2, MYOC, and FABP3) (in bold) were also enriched in these OP- and diabetes-related biological processes and pathways, comparing to the target genes in the TF network." (PMID 36050744, 2022).
diabetic retinopathy (1 paper, 2018). "In accordance with our results two previous studies carried out either to characterize the human plasma proteome or to verify plasma biomarkers for diabetic retinopathy, identified three myocilin peptides in plasma." (PMID 30557320, 2018).
hereditary glaucoma (1 paper, 2019). Hereditary glaucoma is a clinically diverse group of rare eye disorders with genetic predisposition characterized by elevated intraocular pressure (IOP) and glaucomatous changes of the optic nerve head, leading to field defects, visual loss and blindness. "Here, we discuss how issues surrounding antibodies are pertinent to detecting myocilin, a protein found in trabecular meshwork and associated with a portion of hereditary glaucoma." (PMID 31067323, 2019).
malaria (1 paper, 2023). Malaria is a serious and sometimes fatal disease caused by a parasite that commonly infects a certain type of mosquito which feeds on humans. "The presence of MyosinF (MyoF; PF3D7_1329100, previously also MyoC), in the K13 proxiome could indicate an involvement of actin/myosin in endocytosis in malaria parasites." (PMID 38039338, 2023).
Optic neuropathy (1 paper, 2017). "Since the initial association between the myocilin (MYOC) locus and this form of optic neuropathy, several other candidate loci have been related to POAG." (PMID 29104244, 2017).
Primary glaucoma (1 paper, 2021). "Several genes have been demonstrated to be related with primary glaucoma, for example, optineurin (OPTN), myocilin (MYOC), optic atrophy 1, and neurotrophin 413–17." (PMID 34561506, 2021).
retinal degeneration (1 paper, 2022). Degeneration of the retina. "The variable retinal alterations associated with in vivo myocilin overexpression were characterized by areas of retinal degeneration." (PMID 36077382, 2022).
thymoma (1 paper, 2022). A neoplasm arising from the epithelial cells of the thymus. "However, other types of cancer, such as thymoma, exhibit MYOC downregulation, thereby corroborating our results." (PMID 36012492, 2022).
viral infection (1 paper, 2009). "The remaining 10% of cells showed myocilin expression without any prominent signs of viral infection (left row)." (PMID 19287508, 2009).
X-linked recessive disease (1 paper, 2024). X-linked recessive form of disease. "In detail, five autosomal dominant (AD) ophthalmic diseases caused by variants in ABCA4, CRYGD, MYOC, RPL1L1, and TGFBI, one AR disease caused by the PDE6B variant, and one X-linked recessive disease caused by the OCRL variant were determined as genetic causes." (PMID 38785568, 2024).
cancer (14 papers, 2012 to 2025). A tumor composed of atypical neoplastic, often pleomorphic cells that invade other tissues. "The overexpression of MYOC increases muscle mass, and downregulation of myocilin is observed in cancer cachexia, with its loss inducing muscle fiber atrophy and an increase in fibrotic and fatty tissue." (PMID 37576554, 2023). "Its high expression was found to be associated with poor outcomes in a series of different cancers MYOC is a skeletal muscle hypertrophy-promoting protein that was found to be downregulated in multiple cancer cachexia mouse models." (PMID 33597971, 2021). "Additionally, genes like ACTA1, COL4A3, A2M, ADRB2, MYOC, among others, are closely associated with cancer biomarkers, candidate prognostic factors, and therapeutic targets." (PMID 39968416, 2025). "Furthermore, stabilizing MYOC cancer-associated variants could be cancer risk factors for those who carry the mutations." (PMID 38397193, 2024). "The upregulation of MYOC and TBK1 in both conditions may indicate involvement in inflammatory and oxidative stress pathways—mechanisms previously implicated in both neurodegeneration and cancer progression." (PMID 40808675, 2025). "Moreover, at the multi-cancer level, known cancer drivers such as CDC45 and NUF2 were identified to be involved in edgetic gains while NTRK1, PRPH and MYOC were determined to be involved in edgetic losses and may serve as targets for widely applicable therapeutic interventions." (PMID 32152446, 2020).
neurodegenerative disease (2 papers, 2014 to 2025). A disorder of the central nervous system characterized by gradual and progressive loss of neural tissue and neurologic function. "Inspired by recent advances in antibody-based therapeutics to treat protein conformational neurodegenerative diseases, we hypothesized that antibodies could thwart mutant myocilin misfolding and the subsequent accumulation in the ER that confers a toxic gain-of-function and downstream pathology." (PMID 39726989, 2025).
tumor (2 papers, 2019 to 2025). "Specifically, MYOC, TBK1, COL1A1, and COL1A2 were upregulated in tumor tissues, while FOXC1, LRP2, and TEK was downregulated (all p < 0.05)." (PMID 40808675, 2025).
infection (1 paper, 2012). The state of being infected such as from the introduction of a foreign agent such as serum, vaccine, antigenic substance or organism. "Levels of overexpressed MYOC were identical after infections with Q368X and R342K, and about half after D380N, though still at the top of the list." (PMID 22615763, 2012). "RNA was extracted 48 h post-infection and its cDNA assayed for expression of CSTA, using MYOC as a positive control and 18S as the endogenous calibrator." (PMID 22615763, 2012).
metabolic disease (1 paper, 2023). A congenital disorder (due to inherited enzyme abnormality) or acquired (due to failure of a metabolically important organ) disorder resulting from an abnormal metabolic process. "Furthermore, we provide evidence that the AT expression of COBL, MKX and MYOC is related to early signs of AT dysfunction and metabolic disease in children, indicating a potential role in the pathogenesis of these processes." (PMID 36834493, 2023). "However, we detected inverse relationships with MYOC expression with adipocyte size and serum leptin levels as parameters of AT dysfunction as well as with HOMA-IR indicating an association with early signs of metabolic disease." (PMID 36834493, 2023).
MYOC also shares sentences with these, for which no sentence is quoted: Adult onset (2 papers); blinding (2); lung adenocarcinoma (2); Parkinson disease (2); allergic rhinitis (1); anaplastic astrocytoma (1); angle-closure glaucoma (1); asthma (1); Axenfeld-Rieger syndrome (1); blepharospasm (1); colorectal cancer (1); COVID-19 (1); cutaneous melanoma (1); desmoplastic melanoma (1); endocrine system disorder (1); Epiphora (1); glioblastoma multiforme (1); Huntington disease (1); inflammatory bowel disease (1); Kawasaki disease (1); Leber congenital amaurosis (1); lung squamous cell carcinomas (1); lysosomal storage disorders (1); meningoencephalitis (1); microphthalmia (1); mucopolysaccharidosis type 1 (1); myocarditis (1); Onset (1); osteosarcoma (1); ovarian carcinoma (1).
A further 10 diseases each share a sentence with MYOC in 1 paper.